STAT3 (signal transducer and activator of transcription 3)
Diseases named in the same sentence as STAT3 in open-access papers (continued):
Sharing a sentence is not in itself a finding about the gene and the disease.
tumor (continued). "Notably, in TNBC, chromosomal instability (CIN)-driven STING signaling sustains tumor survival via IL-6/STAT3 activation." (PMID 41573551, 2025). "Moreover, because the STAT3 signaling pathway is pivotal for M2 polarization, STAT3 inhibitors have been shown to effectively drive macrophages toward the M1 phenotype and significantly inhibit tumor growth in GBM animal models." (PMID 41002423, 2025). "STAT3 plays a crucial role in cell proliferation and suppression of cell death in many tumor cells." (PMID 39985075, 2025). "Since STAT3 signaling is regulated by molecules such as miRNAs, TLRs, and GPCRs, small‐molecule inhibitors that selectively target these pathways may effectively suppress STAT3 activity, thereby reducing tumor progression and inflammation." (PMID 40166646, 2025). "STAT3 is a transcription factor essential for tumor cell proliferation." (PMID 40924302, 2025). "By doing so, it can downregulate the expression of STAT3, ultimately impeding tumor proliferation." (PMID 40046406, 2025). "The cytokine profile observed in this study, characterized by reduced IL-6 and IL-8 levels with increased TNF-α secretion, suggests that HYP-PDT shifts the tumor microenvironment from a STAT3-dependent pro-tumor state toward an NF-κB–driven pro-inflammatory response." (PMID 41226910, 2025). "Abnormal regulation of STAT3 results in tumor invasion, angiogenesis, and metastasis." (PMID 41195524, 2025). "However, the intricate interplay between STAT3 signaling, tumor biology, and host metabolism remains incompletely understood, necessitating further research to refine therapeutic strategies and validate their clinical efficacy and safety." (PMID 40704145, 2025). "Our experiments found that after Neo-BCV treatment, only the phosphorylation levels of JAK2 and STAT3 in mice subcutaneous tumor tissues were significantly affected, indicating that Neo-BCV specifically inhibits the phosphorylation of JAK2, thereby suppressing the activation of STAT3." (PMID 39852843, 2025). "Besides, immunohistochemistry (IHC) staining showed that the number of STAT3-positive tumor cells in the model group was significantly higher than that in the other two TCM intervention groups." (PMID 41280323, 2025). "Peri-implant inflammation may activate NF-κB and STAT3 signaling, promoting survival, immune evasion, and tumor growth." (PMID 41160384, 2025). "We concluded that, in the comparison between cytokine-stimulated NHL cells expressing mutant STAT1 and WT-expressing control cells, there was a decrease in STAT1-mediated gene expression in the tumor cells, whereas genes upregulated by STAT3 were induced at higher rates." (PMID 40287766, 2025). "Moreover, HIF-1α can interact with other oncogenic pathways, such as PI3K/Akt and STAT3, to form feed-forward loops that enhance tumor aggressiveness and therapy resistance." (PMID 40867898, 2025). "Its mechanisms of action involve apoptosis induction, immune system modulation, and disruption of key oncogenic signaling pathways, including the inhibition of glucose transport via GLUT1 and suppression of JAK2/STAT3 signaling, thereby impeding tumor growth and metastasis." (PMID 40761486, 2025). "Similarly, addition of the STAT3 inhibitor led to downregulation of p-P65, p-STAT3, and PD-L1 in HUVECs treated with tumor supernatants." (PMID 40000620, 2025). "This technique was used to demonstrate that Stat3 was necessary for the development of the tumor." (PMID 41476448, 2025). "STAT3 inhibition can restore the anti-tumor immune response and reduce tumor metastasis." (PMID 40612677, 2025). "STAT3 activation in neutrophils enhances their production of pro-inflammatory cytokines (such as IL-6 and IL-8) and other mediators (e.g., MMPs), which support the tumor’s inflammatory milieu." (PMID 40486614, 2025). "Importantly, SD-36 showed high selectivity for STAT3 over other family members, despite the homologous SH2 domain, and also caused tumor regression in mouse models with minimal toxicity." (PMID 40650173, 2025).
tumor (continued). "Nineteen bioactive compounds in C. lanceolatus displayed a high positive “Z” score, suggesting they might interact with STAT3 and inhibit tumor cell proliferation." (PMID 40061959, 2025). "This suggests that tumor-extrinsic STAT3 function in DCs and T cells play a marked role." (PMID 40356899, 2025). "It has been found that IRSp53 is tyrosine phosphorylated at multiple sites in response to EGFR stimulation, and knocking down of IRSp53 diminished cell proliferation in cells that v-Src transformed and tumor formation in mice through p-AKT/p-Stat3/cyclin D1 signaling pathway." (PMID 41200137, 2025). "In upstream regulation of the PD‐1/PD‐L1 pathway, STAT3, as a key transcription factor, regulates expression of immunosuppressive factors such as PD‐L1 and IL‐10, playing important roles in immune escape and tumor progression." (PMID 41049269, 2025). "Persistent activation of NF-κB and IL-6/STAT3 signaling modifies splicing patterns, increases proteostatic burden, and upregulates ribosome biogenesis, thereby reinforcing the chronic microinflammatory state that promotes tumor initiation and progression." (PMID 41514860, 2025). "Though paradoxical, tumor tissues may up- and downregulate myeloid cell STAT3 activity due to time and space." (PMID 40422244, 2025). "This STAT3-mediated enhancement of immune checkpoint expression contributes to tumor immune evasion and may help explain the limited efficacy of immune checkpoint blockade therapy in end-stage cancer patients, particularly those suffering from cancer cachexia." (PMID 40704145, 2025). "Additionally, STAT3 contributes to the regulation of immune responses within various tumor microenvironments (TMEs)." (PMID 40166646, 2025). "Moreover, elevated JAK2/STAT3 pathway activation in TNBC associates with resistance to targeted therapies and promotes more invasive tumor characteristics." (PMID 40649917, 2025). "In addition, inflammatory mediators often activate oncogenic transcription factors such as NF-κB and STAT3, while inflammation can stimulate tumor angiogenesis, tumor invasiveness and metastatic dissemination." (PMID 40722593, 2025). "Signal transducer and activator of transcription 3 (STAT3) is overexpressed in various cancers and acts as a critical signaling hub in tumor cells and cellular components of the TME, especially tumor-infiltrating immune cells, controlling cell proliferation, migration, and apoptosis." (PMID 39941714, 2025). "In addition, IL-6 directly promotes the proliferation, survival, and invasion of tumor cells by activating STAT3 signaling." (PMID 41376630, 2025). "Notably, TNF-alpha signaling via NF-κB and IL6/JAK/STAT3 signaling have been widely characterized to foster an inflammatory tumor microenvironment that favors metastasis." (PMID 39489818, 2025). "STAT3 is a master regulator of most key hallmarks and enablers of cancer, including cell proliferation, apoptosis resistance, metastasis, immune evasion, tumor angiogenesis, epithelial–mesenchymal transition, DNA damage response, and the Warburg effect." (PMID 39792482, 2025). "To gain further insight into whether MCPIP1 intervenes in PC hybrid EMT and tumor stemness by regulating the IL6/JAK/STAT3 signaling pathway, we treated sh‐MCPIP1 PC cell lines with the IL6 inhibitor LMT‐28." (PMID 40874680, 2025). "Building upon these findings, we reasoned that the depletion of SNRPE might trigger ROS-mediated pyroptosis through targeting STAT3 in tumor cells." (PMID 40386046, 2025). "STAT3 also sustains constitutive NF-κB activity in tumor cells, prolonging its nuclear retention and amplifying cancer-associated NF-κB signaling, which collectively induces the expression of genes implicated in proliferation, anti-apoptosis, angiogenesis, and metastasis." (PMID 41000397, 2025). "There are various possible mechanisms by which STAT3 functions as a tumor suppressor." (PMID 41104968, 2025).
tumor (continued). "Similar combinatorial methods are consistent with our results on the synergistic impact of Concanavalin A and Silibinin, both of which not only display cytotoxic and pro-apoptotic activities, but additionally inhibit STAT3 signaling, a critical modulator of immune suppression and tumor progression." (PMID 40350446, 2025). "Dysregulated STAT3 activation supports tumor proliferation, survival, and immune evasion." (PMID 40427086, 2025). "For example, knocking down FOXM1 or STAT3 in proximal models may reduce tumor growth, while overexpressing CDX2 or GATA6 could induce a more differentiated, less aggressive phenotype, advancing therapeutic understanding and precision medicine." (PMID 40862793, 2025). "Tumor progression, STAT3 expression levels, and survival rates were analyzed." (PMID 40427146, 2025). "Importantly, TGFβ is a well-established mediator of myeloid immune suppression and tumor-promoting inflammation and has been shown to cooperate with STAT3 signaling to reinforce pro-tumorigenic immune phenotypes." (PMID 41514627, 2025). "Previous studies found that the JAK2/STAT3 pathway activates the apoptosis inhibitors survivin, Mcl-1, Bcl-2, and Bcl-XL to block the caspase cascade and the initiation of apoptotic mechanisms in tumor cells." (PMID 40519928, 2025). "Moreover, inflammatory signaling pathways, such as NF-κB and STAT3, further amplify tumorigenesis by promoting tumor cell proliferation, survival, and immune evasion." (PMID 39941451, 2025). "Although JAK2 and STAT3 expression levels were not significantly correlated with prognosis in this study, it is noteworthy that these two genes have been implicated in tumor microenvironment regulation in other cancer types." (PMID 40978029, 2025). "Given the pivotal role of the IL6/JAK2/STAT3 axis in promoting tumor progression and shaping an immunosuppressive microenvironment, we performed immunohistochemical analysis of phosphorylated JAK2 and STAT3 in tumor tissues from the mouse model to validate pathway activation." (PMID 40384867, 2025). "STAT3 plays a critical role in glucose metabolism by regulating the expression of genes involved in glycolysis and oxidative phosphorylation, thereby affecting the energy metabolism of tumours." (PMID 39778006, 2025). "Likewise, transcriptional proteins such as NF-κB, and STAT3 are found to be dysregulated in several tumor types including neuroblastoma." (PMID 40722593, 2025). "Studies have shown that exposure of fibroblasts to tumor inflammation triggers epigenetic transitions mediated by histone acetyltransferases and DNA methyltransferases, leading to sustained activation of STAT3 which is critical for the maintenance of CAF phenotype and function." (PMID 40703348, 2025). "In addition, tumor-associated macrophage-derived CXCL1 adds a further layer of regulation by activating IGF1R, leading to STAT3 phosphorylation and subsequent transcriptional upregulation of HMGB1, which drives autophagy and increases ABCG2 expression." (PMID 41465435, 2025). "Non-canonical functions of PKM2 include its SUMOylation, which promotes interaction with ARRDC1 and secretion via exosomes into the tumor microenvironment, activating STAT3 phosphorylation in monocytes and inducing their metabolic reprogramming and differentiation into macrophages." (PMID 40842995, 2025). "However, silencing LCN2 in tumor cells significantly attenuated these markers and reduced STAT3 phosphorylation in fibroblasts, indicating that LCN2 is a necessary paracrine effector downstream of EGFRvIII." (PMID 40472740, 2025).
tumor (continued). "Similarly, the NF-κB and STAT3 pathways are activated by pro-inflammatory cytokines (e.g., IL-6 and IL-1β) secreted by tumor cells, driving pro-fibrotic and immunosuppressive effects." (PMID 40137490, 2025). "STAT3 activation upregulates anti-apoptotic proteins (e.g., Bcl-2) and promotes cell cycle progression through the regulation of cyclins and cyclin-dependent kinases, ultimately contributing to chemoresistance in tumor cells." (PMID 40404908, 2025). "In agreement with the results from skeletal muscle, we found a clear positive correlation between hepatic STAT3 phosphorylation (Tyr705) and weight loss in tumor-bearing mice, which did not occur in non-tumor-bearing mice or an overnight fast." (PMID 41278737, 2025). "IL-6 promotes the activation of signal transducer and activator of transcription 3 (STAT3) signaling in both tumor cells and infiltrating immune cells, leading to increased proliferation, survival, and expansion of regulatory immune subsets such as Tregs and MDSCs." (PMID 41179287, 2025). "STAT3 plays an important carcinogenic role in malignant and precancerous cells and may also inhibit tumor promotion through its anti-inflammatory effects in inflammatory cells." (PMID 40841364, 2025). "Moreover, the multi-kinase inhibitor sorafenib has demonstrated the ability to modulate STAT3 activity, preventing the accumulation of atrogin-1 and Pax7 in skeletal muscle, thereby improving functional capacity and reducing fatigue in tumor-bearing animals." (PMID 40704145, 2025). "For instance, cytokines in the tumor microenvironment (e.g., IL‐6) may activate STAT3 through bypass pathways, thereby compromising the efficacy of SRC‐1 inhibitors." (PMID 40985319, 2025). "In addition, IL-24 activates STAT3, which often predicts tumor progression, and VG9-IL-24 can counteract the tendency of STAT3 phosphorylation." (PMID 40469178, 2025). "Besides tumor intrinsic effects, activated STAT3 also has been shown to inhibit the activity of T-cell directed immunotherapy by supporting T-regs, immunosuppressive macrophages and MDSCs in the TME." (PMID 40529368, 2025). "Secondly, for inhibiting apoptosis, IL-6 activates STAT3 to enhance the expression of anti-apoptotic proteins like Bcl-2 and Bcl-xL, while concurrently repressing pro-apoptotic proteins such as caspase-3, thereby enabling tumor cells to evade apoptosis." (PMID 39980561, 2025). "-High relevance: IL-11/p-STAT3 axis critical for shaping immunosuppressive tumor microenvironment." (PMID 40650089, 2025). "In recent years, inhibitors targeting key signaling pathways, such as AKT, MAPK/ERK, and STAT3, have gained prominence in cancer therapy due to their critical roles in the regulation of tumor growth, survival, and metastasis, thereby making them prime targets for therapeutic intervention." (PMID 40362400, 2025). "Activation of STAT3 signaling promotes the secretion of S100A8/A9, a heterodimeric calcium-sensing damage-associated molecular pattern (DAMP), which binds to Toll-like receptor 4 (TLR4) on adjacent tumor cells." (PMID 40948745, 2025). "Similarly, IL-6 produced by CAFs exerts paracrine effects distinct from tumor-derived IL-6, preferentially activating STAT3 signaling in adjacent immune and epithelial cells." (PMID 41179287, 2025). "Additionally, targeting the STAT3-ferroptosis axis has proven effective in curbing tumor growth and reducing chemoresistance in GC." (PMID 41007830, 2025). "Emerging evidence suggests that modulation of the immune response through inhibition of these kinases, particularly via the cGAS-STING pathway and STAT1/STAT3 transcription factors, which activate a type I interferon response and upregulate PD-L1, contributes to anti-tumor immunity." (PMID 40977887, 2025). "In neutrophil-STAT3 deficient mice, we observed a significant increase in CD8+ T cell populations with high cytotoxic signature, which is likely responsible for the observed decrease in tumor growth and metastasis." (PMID 40885734, 2025).
tumor (continued). "The co-expression and interaction of CEBPB and STAT3 may enhance oncogenic processes in ccRCC, contributing to its aggressive nature by shaping the tumor microenvironment through immune cell recruitment and activation." (PMID 40949418, 2025). "Furthermore, the combined inhibition of MEK and STAT3 has exhibited beneficial effects on tumor fibrosis." (PMID 40075563, 2025). "These include IL-6 blocker stuximab, IL-6R receptor blocker tolizumab, JAK inhibitor ruxolitinib, and STAT3 inhibitors, which have been shown in preclinical experiments to significantly inhibit tumor growth, increase immune cell numbers, and improve the immunosuppressive microenvironment." (PMID 40433391, 2025). "Recent studies indicate that pS727 may influence STAT3’s oncogenic potential by supporting mitochondrial biogenesis and modulating reactive oxygen species (ROS) production, which can contribute to tumor progression under hypoxic conditions." (PMID 40075607, 2025). "ROS originating from mitochondria are crucial in driving tumor progression, therefore BNP may indirectly affect tumor progression through the STAT3-Opa1 signaling pathway." (PMID 40877221, 2025). "Additionally, our results show that targeting STAT3 does not only affect tumor cells but repolarizes the TIME to an anti-tumor phenotype." (PMID 40356899, 2025). "Additionally, DNTTIP2 is involved in the IL6/JAK/STAT3 signaling pathway, which is key to tumor growth and immune evasion." (PMID 40577282, 2025). "The STAT3 signaling pathway is critical in regulating immune responses and promoting tumor growth." (PMID 40057744, 2025). "Notably, the silencing of MUC2 increases IL-6 secretion, which activates the STAT3 signaling pathway, promoting tumor cell migration, epithelial-mesenchymal transition (EMT), and metastasis." (PMID 41378310, 2025). "This suppression of STAT1- and STAT3-target genes suggests that chalcone-9 may disrupt tumor cell functions related to those genes." (PMID 40199813, 2025). "Furthermore, the hyperactivation of the IL-6/JAK/STAT3 signaling pathway can suppress antitumor immune responses in the tumor microenvironment, allowing cancer to persist." (PMID 40558287, 2025). "DIA confirmed elevated STAT3 in tumor versus normal tissue (p < 0.05)." (PMID 40636126, 2025). "Therefore, this study not only evaluates the potential of BZN as an anti-tumor drug or drug lead for HNSCC but also offers new insights into the development of novel STAT3 inhibitors." (PMID 40242440, 2025). "In addition, Ginsenoside Rg3 combined with ART treatment significantly inhibits tumor growth in mice (inoculation of HepG2 SR cells into mice) and suppresses the phosphorylation of STAT3 and its upstream kinase, Src, in HepG2 cells." (PMID 40142963, 2025). "Additionally, circ-HSP90A stabilizes HSP90A and activates STAT3 signaling, further promoting tumor progression and resistance to immune responses." (PMID 40739089, 2025). "For NSCLC perioperative care, an alginate hydrogel loaded with endoplasmic reticulum–modified liposomes co-delivering STAT3 siRNA and lidocaine induces tumor apoptosis, promotes M1 macrophages, decreases malignant pleural effusion, and relieves pain after a single application." (PMID 41304838, 2025). "Additionally, sesamin inhibits MMP2 expression by downregulating the STAT3 signaling pathway, leading to reduced tumor cell migration, invasion, and anoikis resistance." (PMID 40303286, 2025). "Similarly, IL-10, secreted by immune cells and M2 macrophages, induces STAT3 activation in regulatory T cells and tumor cells, promoting migration, invasion, and epithelial–mesenchymal transition (EMT)." (PMID 41155242, 2025). "This leads to the downregulation of key downstream targets of STAT3, inhibiting tumor cell growth." (PMID 40118821, 2025).